CYP7A1 (cytochrome P450 family 7 subfamily A member 1)
Diseases named in the same sentence as CYP7A1 in open-access papers (continued):
Sharing a sentence is not in itself a finding about the gene and the disease.
steatosis (continued). "Of the top-ranked 10 genes, two genes (CYP7A1 and PEG10) were significantly up-regulated in both steatosis and NASH patients, while eight genes (FOSB, FOS, IL6, GADD45G, MYC, SLITRK3, JUNB, and IGFBP2) were significantly down-regulated." (PMID 33324350, 2020). "Analyses were conducted on the following outcomes: steatosis, ballooning hepatocytes, NAS-index, fibrosis, IL-8, MCP-1, TNF-α, α-sma, Col1a1, TGF-β, CYP7A1, HC and HT." (PMID 32882802, 2020). "Treatment with BAR502 caused a ≈10% reduction of b.w., increased insulin sensitivity and circulating levels of HDL, while reduced steatosis, inflammatory and fibrosis scores and liver expression of SREPB1c, FAS, PPARγ, CD36 and CYP7A1 mRNA." (PMID 28202906, 2017). "Both IHC analysis and western blot assays showed the proteins of CYP7A1, PGC-1α, PPARα, CPT1A and ACOX1 were decreased in livers tissues from patients with steatosis when compared with ones without steatosis." (PMID 29022907, 2017).
Insulin resistance (22 papers, 2011 to 2025). Increased resistance towards insulin, that is, diminished effectiveness of insulin in reducing blood glucose levels. "Correspondingly, the DB group in the present study exhibited higher insulin resistance and expressed lower levels of CYP7A1 and CYP8B1, while XB supplementation significantly upregulated these enzymes." (PMID 27929393, 2016). "It remains undetermined whether or not the decreased Cyp7a1 expression in InsrP1195L/+/HFD liver is the primary or a secondary change induced by HFD feeding plus insulin resistance." (PMID 26615883, 2015).
liver fibrosis (16 papers, 2017 to 2025). "All these findings demonstrate that bile acid 7α‐dehydratase, which is expressed in C. scindens, leads to the inhibition of hepatic CYP7A1 expression, thereby attenuation of liver fibrosis." (PMID 39680750, 2025). "Liver fibrosis development significantly reduced the expression of Bsep, CYP7A1, Mrp2, and FXR (p < 0.001 vs. control group)." (PMID 39195542, 2024). "The decrease in intestinal bile leads to a deficiency in intestinal FXR activity, which weakens the inhibitory effect of CYP7A1 and leads to increased bile acid production and aggravation of liver fibrosis." (PMID 35770078, 2022). "During hepatic fibrosis, CYP7A1 expression in the classic pathway is inhibited by pro-inflammatory cytokines, which results in dysmetabolism of bile acids." (PMID 31214133, 2019). "The mRNA expression levels of key enzymes in classical or alternative BA synthesis pathways, Cyp7a1 and cytochrome P450 family 7 subfamily B member 1 (Cyp7b1), were significantly increased in the moderate liver fibrosis stage and tended to increase in the advanced fibrosis stage." (PMID 35637968, 2022). "Consistent with the gene expression trend, higher CYP7A1 and lower CYP8B1, FXR, and SHP protein levels were observed in the liver fibrosis groups." (PMID 35637968, 2022). "The expression of Cyp7a1 and Akr1d1 was not significantly downregulated in rats with hepatic fibrosis, but this trend was significantly reversed after the transplantation of ADMSCs." (PMID 38003277, 2023).
diabetes (14 papers, 2012 to 2025). "Their study indicates the existence of two interacting variants, rs3808607 and rs9297994, which modulate CYP7A1 expression and are associated with the risk of coronary heart disease and diabetes." (PMID 40806580, 2025). "Since CYP7A1 polymorphisms have been associated with diabetes, and given that the SA and control groups were different in diabetes frequency, we performed a statistical sub-analysis that excluded patients with diabetes." (PMID 39207177, 2025). "Diabetes has been associated with increased total bile acids, and this has previously been attributed to hyperglycaemia-induced CYP7A1 histone acetylation." (PMID 35883432, 2022). "Therefore, this study was not powered to perform more detailed statistical analyses with diabetes, but it sets a precedent to further explore the effect of CYP7A1 gene polymorphisms on cardiovascular complications in diabetic patients." (PMID 38540230, 2024). "Glucose stimulates bile acid production by increasing CYP7A1 expression which may provide a mechanism for the increased bile acid excretion in poorly controlled type 2 diabetes mellitus, and the correlation we have found between bile acid excretion and HbA1c." (PMID 24736330, 2014). "Therefore, Cyp7a1 may serve as a potential candidate therapeutic node for diabetes." (PMID 29744368, 2018). "Several genes encoding proteins known to be related to cholesterol metabolism and transport (CYP7A1, HMGCR) and genes involved in non-insulin dependent diabetes mellitus (GCK, PNPLA3) were down-regulated 3- to 23-fold." (PMID 26442469, 2015). "A common pattern emerged whereby patients that do not remit diabetes (T2D-NoR) displayed signifciantly higher expression levels for FGF21, HNF4α, CYP7A1, β-Klotho, GS, and FGFR4, compared to the No-T2D and T2D-R groups." (PMID 25664662, 2015). "Moreover, hepatic expression levels of FGF21, CYP7A1, HNF4α, β-Klotho, FGFR4, and GS were higher in T2D patients that do not remit diabetes after RYGB surgery." (PMID 25664662, 2015).
gallstones (14 papers, 2009 to 2025). Solid crystalline precipitates in the biliary tract, usually formed in the gallbladder, resulting in the condition of cholelithiasis. "In contrast, reduced function of CYP7A1, the rate-limiting enzyme in the conversion of cholesterol to bile acids in the liver, likely predisposes to gallstone formation through a decrease in bile acid synthesis." (PMID 30504769, 2018). "Several studies have evaluated genetic variations in the CYP7A1 gene in relation to gallstone disease risk, with stronger links found to genetic predisposition in males compared to females, while a deficiency in the enzyme is associated with gallstone formation." (PMID 36836631, 2023). "The inactivation of CYP7A1 contributed to gallstone formation by decreasing the production of BAs and increasing cholesterol accumulation." (PMID 39052638, 2024). "In Chilean Hispanic and Mapuche subjects (known to have one of the highest incidences of gallstones worldwide), an increase in CYP7A1 expression and an increase in bile acid excretion resulted in a higher incidence of gallstone formation." (PMID 36836631, 2023). "As CYP7A1 regulates the first step of bile acid synthesis, it has been extensively investigated in relation to gallstone formation." (PMID 36836631, 2023). "We have previously reported that the expression of MDR3, MRP3, and MRP4 were increased whereas NTCP and CYP7A1 were decreased in human obstructive cholestasis originating from gallstone blockage of bile ducts." (PMID 25798860, 2015). "Deficiency in CYP7A1 manifests with markedly elevated total cholesterol and LDL-C, premature gallstones, and premature coronary and peripheral vascular disease." (PMID 22607622, 2012). "Relative to Admirand’s theory, lower CYP7A1 activity compromises the conversion of cholesterol to bile acid, resulting in increased cholesterol excretion and decreased bile acid excretion, favoring gallstone formation." (PMID 36836631, 2023). "Alternatively, loss of gallbladder function because of the presence of gallstones, or cholecystectomy could change the daily secretion pattern of FGF19 with the subsequent modification of the circadian rhythm of CYP7A1 mRNA." (PMID 19995447, 2009). "In our findings, however, among HIV-positive patients with gallstones, HNF4α was reduced in comparison to the levels in HIV-negative patients, yet CYP7A1 was upregulated." (PMID 36836631, 2023). "Our study indicates that MIC-1 influences gallstone formation by increasing AMPK phosphorylation, reducing CYP7A1 and HMGCR expression, and increasing ABCG5 and ABCG8 expression." (PMID 37310967, 2023). "This demonstrates that HNF4α on its own is not a regulator of CYP7A1 in the pathogenesis of gallstones in HIV-positive patients." (PMID 36836631, 2023). "Thus, increasing the expression levels of ABCG8, ABCB11, CYP7A1 and CYP27A1 or decreasing the levels of LXR and PPAR-α can stimulate bile acid secretion and efficiently facilitate gallstone dissolution to reverse damage to the hepatocytes." (PMID 32615989, 2020). "CYP7A1, CYP7B1, LXR, and HMGCR mRNA may be efficient targets of YCHD, which may be a preventive drug to reverse liver injury, normalize bile lipids, facilitate gallstone dissolution, and attenuate gallstone formation." (PMID 30310412, 2018).
hepatoma (13 papers, 2008 to 2025). "It has been well documented that PPARα activators suppress CYP7A1 gene promoter activity in human hepatoma HepG2 cells and that PPARα agonists, e.g., fenofibrate, downregulate cyp7a1 and cyp27a1 expression and reduce their activity in rodents." (PMID 39120326, 2024). "In another study, chlorogenic acid increased TC efflux by upregulating the gene expression of LXRα and CYP7A1 in human hepatoma HepG2 cells." (PMID 36014836, 2022). "GSEA employing the c2.all.v2022.1.Hs.symbols.gmt curated gene set further revealed that disulfidoptosis in hepatocellular carcinoma is fundamentally orchestrated by hepatic metabolic reprogramming, notably suppression of bile acid biosynthesis (e.g., CYP7A1/CYP27A1)." (PMID 40790550, 2025). "For example, NR2F2 has been shown to determine hepatoma phenotype by acting both as a transcriptional repressor of microsomal triglyceride transfer protein (MTP) and an inducer of CYP7A1." (PMID 20195529, 2010). "Furthermore, both in the murine hepatocyte, Hepa1-6, and human hepatoma cells, HuH7, a dose-dependent induction of FXR and inhibition of CYP7A1 expression was found." (PMID 35017486, 2022).
lipid metabolism disorders (8 papers, 2020 to 2025). "Mechanistically, loss of Mettl3 significantly downregulated the expression levels of multiple m6A-modified mRNAs related to lipid metabolism, including Adh7, Cpt1a, and Cyp7a1, further promoting lipid metabolism disorders and liver injury in mice." (PMID 37335109, 2023). "Decreases the relative expression levels of SREBP-2 and HMG-CoA reductase, TC contents in blood and liver, increases the expression level of CYP7A1 to improve lipid levels in blood and lipid metabolism disorders." (PMID 35548468, 2022). "The small-molecule peptides in the earthworm protein hydrolysate alleviated lipid metabolism disorders in steatotic hepatocytes by regulating the expression levels of crucial proteins (APOC3, HMGCR, PCSK9, PPAR-Y, SREBP1, C/EBP-a, NPC1L1, CYP7A1)." (PMID 40647090, 2025).
hypertriglyceridemia (7 papers, 2006 to 2025). A laboratory test result indicating elevated triglyceride concentration in the blood. "Besides, rare mutations in cytochrome P450 family 7 subfamily A member 1 (CYP7A1) gene also result in premature GSD and hypertriglyceridemia, and the product of CYP7A1 gene catalyzes the initial steps of cholesterol catabolism and cholic acid synthesis." (PMID 35236330, 2022). "CYP7A1 deficiency caused by a homozygous deletion mutation could reduce the conversion of cholesterol to bile acids, resulting in accumulation of cholesterol in the liver, leading to downregulation of LDL receptors and consequent elevated LDL cholesterol and hypertriglyceridemia." (PMID 29721023, 2018).
type 2 diabetes (6 papers, 2014 to 2024). "Here, the protein abudance of CYP7a1 was decreased in MetS group, which was also found the same trend in type 2 diabetes rats." (PMID 35789338, 2022). "Consistent with our findings, a recent study showed that exogenous administration of the FGF19 analog NGM282 did not correct hyperglycemia in patients with type 2 diabetes (T2D) but instead caused a rapid and sustained reduction in hepatic Cyp7a1 levels and liver fat content in patients with MASLD." (PMID 38587078, 2024). "Rodent models of type-2 diabetes also exhibit reduced hepatic FXR expression, paralleled by an increased expression of CYP7A1 in the liver and an increased BA pool." (PMID 38137523, 2023).
cerebrotendinous xanthomatosis (5 papers, 2023 to 2025). Cerebrotendinous xanthomatosis (CTX) is an anomaly of bile acid synthesis characterized by neonatal cholestasis, childhood-onset cataract, adolescent to young adult-onset tendon xanthomata, and brain xanthomata with adult-onset neurologic dysfunction. "The marked increases of Cyp7a1 and Ntcp expressions have been observed in the liver with decreased BAs of the patients with cerebrotendinous xanthomatosis which is the inherited deficiency of key-enzyme (sterol 27-hydroxylase) in BA synthesis, although the FXR–SHP pathway was normally activated." (PMID 37512531, 2023). "The authorization for indications sterol 27-hydroxylase (cerebrotendinous xanthomatosis, CTX), α-methylacyl-CoA racemase (AMACR) deficiency and cholesterol 7α-hydroxylase (CYP7A1) deficiency was withdrawn in 2020 at the request of the marketing authorization holder due to commercial reasons." (PMID 39702264, 2024). "Until 2020, CA was also authorized in the EU for the indications sterol 27‐hydroxylase deficiency (causing cerebrotendinous xanthomatosis, CTX), α‐methylacyl‐CoA racemase (AMACR) deficiency, and cholesterol 7α‐hydroxylase (CYP7A1) deficiency." (PMID 40643170, 2025).
coronary artery disease (5 papers, 2015 to 2025). "Nonetheless, recent studies have shown that some genetic variants in the enhancer and promoter regions of the CYP7A1 gene reduce the expression of the CYP7A1 enzyme, increasing plasma lipid levels, as well as the risk of developing coronary heart disease." (PMID 39207177, 2025). "The association between the rs7833904 polymorphism of the CYP7A1 gene and coronary artery disease was described for the first time." (PMID 25944972, 2015). "Moreover, a few of these studies reported the associations between the CYP7A1 gene polymorphisms and such diseases like gallbladder stone, gallbladder cancer, proximal colon cancer, neuromyelitis optica, or coronary artery disease." (PMID 25944972, 2015).
Hyperglycemia (5 papers, 2021 to 2024). An increased concentration of glucose in the blood. "Exogenous administration of FGF19 and its analog NGM282 did not correct hyperglycemia in diabetic patients, but caused a rapid and sustained reduction in hepatic Cyp7a1 levels and liver fat content in NAFLD patients." (PMID 34362888, 2021).
non-alcoholic fatty liver disease (5 papers, 2021 to 2025). "HDCA intervention has been found to alleviate human non-alcoholic fatty liver disease (NAFLD) by activating the alternative pathway centered on CYP7B1, inhibiting the classical pathway centered on CYP7A1, altering the bile acid synthesis pathway in the liver." (PMID 41470884, 2025). "Since CYP7A1 is the rate-limiting enzyme in bile acid synthesis, OCA can inhibit bile acid synthesis and is used to treat primary biliary cholangitis and non-alcoholic fatty liver disease." (PMID 38542397, 2024). "It is of interest to note that ursodeoxycholic acid (UDCA), a C7 epimer of CDCA, has been suggested as an FXR antagonist in non-alcoholic fatty liver disease (NAFLD) patients; this lowers FGF19 levels while inducing cholesterol 7α-hydroxylase (CYP7A1), a rate-limiting enzyme of BA biosynthesis." (PMID 40565288, 2025).
colitis (4 papers, 2021 to 2024). Inflammation of the colon. "Recombinant fibrinogen-like protein 2 improved DSS-induced colitis by reversing the decline in gut microbiota diversity and restoring BA homeostasis by decreasing total BA, increasing FXR and FGF15, and downregulating CYP7A1." (PMID 39767816, 2024). "In addition, the expression of CYP7A1, the rate-limiting enzyme in classical bile synthesis pathway, was significantly increased in FMT-colitis group mice." (PMID 36735734, 2023).
intrahepatic cholestasis (4 papers, 2023 to 2025). A cholestasis characterized by impairment of the bile flow caused by obstruction located in the liver. "Our previous research indicated that PDE could cause maternal intrahepatic cholestasis during pregnancy (ICP) likely related to increased expression of estrogen receptor α (ERα) and CYP7A1 in the maternal liver." (PMID 40046408, 2025).
liver cancer (4 papers, 2015 to 2024). An epithelial or non-epithelial malignant neoplasm that arises from the liver. "NR0B2 has been associated with only 4 alerts that pertained to protection against viral hepatitis-related liver cancers and the repression of bile acid biosynthesis (i.e., via downregulation of Cyp7a1)." (PMID 39065726, 2024). "Therefore, the observed sex difference in FXR, BSEP, NTCP, CYP7A1 and CYP7B1 gene expressions may result in changes in enterohepatic circulation/BA synthesis and the differential accumulation of cytotoxic BAs in hepatocytes, thus contributing to a higher liver cancer incidence in male mice." (PMID 28345673, 2017).
primary biliary cholangitis (4 papers, 2015 to 2025). Primary biliary cholangitis (PBC) is a chronic and slowly progressive cholestatic liver disease of autoimmune etiology characterized by injury of the intrahepatic bile ducts that may eventually lead to liver failure. "However, only CYP7A1 repression was detected in human obstructive cholestasis and primary biliary cirrhosis (PBC)." (PMID 25798860, 2015).
cholelithiasis (3 papers, 2025). The presence of crystallized deposits forming in the gallbladder or biliary tree, primarily composed of cholesterol, bilirubin, and bile. "PPARα suppresses the activity of cholesterol 7α-hydroxylase (CYP7A1) and sterol 27-hydroxylase (CYP27A1), the rate-limiting enzymes in bile acid synthesis, leading to a decrease in bile acid production and the likely development of biliary tract–related adverse effects, including cholelithiasis." (PMID 41368577, 2025).
Cholestatic liver disease (3 papers, 2019 to 2024). "As expected, serum FGF19 correlates with severity of cholestatic liver disease where increases in serum FGF19 is associated with a decrease in CYP7A1 expression." (PMID 33414764, 2020). "Impeding the synthesis of bile acids by downregulation of CYP7A1 has become a widely adopted approach in the treatment of cholestatic liver diseases." (PMID 39618181, 2024). "Activation of PPARα had a beneficial effect on cholestatic liver diseases, and was mainly involved in the inhibition of CYP7A1 and upregulation of CYP3A4, UGT1A, and SULT2A1, and induction of MDR2 to increase biliary phospholipids secretion." (PMID 30774596, 2019). "Additionally, the hepatic knockdown of Cyp7a1 further demonstrated that inhibiting hepatic bile acid synthesis might be the main pathway through which SIRT6 alleviates cholestatic liver disease." (PMID 39618181, 2024).
Smith-Lemli-Opitz syndrome (3 papers, 2017 to 2020). Smith-Lemli-Opitz syndrome (SLOS) is characterized by multiple congenital anomalies, intellectual deficit, and behavioral problems. "Both 7-OC and 7β-HC are abundant in the disease Smith Lemli Opitz Syndrome (SLOS) where 7-DHC, the CYP7A1 substrate, is present at elevated concentrations." (PMID 28411018, 2017).
tuberculosis (3 papers, 2014 to 2021). A chronic, recurrent infection caused by the bacterium Mycobacterium tuberculosis. "The CYP7A1 gene rs3808607 variant is associated with susceptibility of tuberculosis in Moroccan population." (PMID 27896281, 2016).
Viral infection (3 papers, 2010 to 2023). "Among them, 22 genes (Gm26130, mt-Ts2, Mgst2, Cyp7a1, Vps45, etc.)were clustered as a hot block next to a block containing Irf7 gene that is the master regulator for the induction of type I interferon during viral infection." (PMID 25902143, 2015). "Down-regulation of IL15, NOS2A, CCR4 and up-regulation of IL17, CYP7A1, SELE, IL5, RPL3L genes in both patient categories indicative of response to p-H1N1-09 virus infection." (PMID 20957032, 2010).